TLR2 (toll like receptor 2)
Diseases named in the same sentence as TLR2 in open-access papers (continued):
Sharing a sentence is not in itself a finding about the gene and the disease.
Hyperglycemia (27 papers, 2012 to 2025). An increased concentration of glucose in the blood. "In the pathogenesis of DR, oxidative stress caused by hyperglycemia triggers the expression of toll-like receptor-2 (TLR-2), TLR-4, and NF-κB through ROS." (PMID 40109357, 2025). "Hyperglycemia of retinal ganglion cells increases the expression of TLR2 and TLR4, leading to the expression of proinflammatory molecules localized in the retinal area." (PMID 40076851, 2025). "Data can be accessed at: Jiménez-Escutia, Rodrigo; Olmos-Ortiz, Andrea (2025), “Hyperglycemia Enhances Group B Streptococcus Pathogenicity by Impairing TLR2 Expression and Chemotactic Response in the Human Placenta”, Mendeley Data, V1." (PMID 40746553, 2025). "Previous studies have demonstrated that hyperglycemia activates the innate immune response mediated by TLR2, TLR4, and the NLRP3 inflammasome, inducing the production of various proinflammatory cytokines, including IL-1β, IL18, IL-6, and TNFα." (PMID 34356130, 2021). "Here, we demonstrated that, in the setting of hyperglycemia, TLR2+/+ mice triggered increased pro-inflammatory, but reduced fungicidal activity compared with TLR2−/− mice." (PMID 28164040, 2017). "The TLR2 up-regulates in monocytes under hyperglycemia in type I and type II diabetic patients, and the TLR2 expression is enhanced in patients with diabetic nephropathy." (PMID 24835775, 2014). "Our results support the hypothesis that hyperglycemia may impair the placenta’s ability to detect GBS via TLR-2, even in the presence of increased bacterial load." (PMID 40746553, 2025). "In patients with type 2 diabetes, hyperglycemia upregulates TLR2 and TLR4 expression in monocytes." (PMID 40429692, 2025). "Furthermore, the upregulation of NOX1 by hyperglycemia induced activation of the TLR2/NF-κB pathway both in vitro and in vivo, whereas these effects were significantly attenuated with NOX1 gene silencing and further enhanced with NOX1 gene overexpression." (PMID 36225554, 2022). "Through this study, a conclusion could be made that WEM mitigates hyperglycemia, IR, and inflammation through the interactions among TLR2 signalling pathway, insulin signalling pathway and TNF-α." (PMID 31752797, 2019). "However, using the in vitro model of hyperglycemia at 30 mM glucose, we found that cytokine production was diminished after TLR-2 and TLR-4 activation and that the intracellular growth of M. tuberculosis in human monocytes was not controlled." (PMID 31815150, 2019). "However, TLR2−/− mice display increased clearance of Dermatophyte Trichophyton mentagrophytes in the setting of hyperglycemia." (PMID 28979269, 2017). "It is not clear whether hyperglycemia could upregulate TLR8 expression, and a few studies both in humans and mice have shown the link between hyperglycemia and TLR2/4 induction and upregulation." (PMID 27980459, 2016). "The hyperglycemia could elevate the expression of TLR2 mRNA in a time-dependent manner." (PMID 31752797, 2019). "Besides, the important role of TLR2 to interfere in the immune response during dermatophyte infection, especially in the setting of hyperglycemia as demonstrated in the present study, Dectin-1 has emerged as a crucial PRR involved in the immunology of dermatophytosis." (PMID 28164040, 2017). "Thus, it may be speculated that hyperglycemia and free fatty acids may play a significant role in inducing and activating inflammatory signaling via TLR2/4 pathways." (PMID 26312071, 2015). "This increase in TLR2 and TLR4 activity is accompanied by a pro-inflammatory state and hyperglycemia." (PMID 40076851, 2025). "The combined stimulus of hyperglycemia and GBS resulted in reduced placental expression of TLR-2, TNF-α, MCP-1, and MIP-1β, thereby impairing the chemotaxis of IVMC, monocytes, and NK cells." (PMID 40746553, 2025). "It has been reported that hyperglycemia stimulates NADPH oxidase in the PKC pathway, thereby inducing TLR-2 and TLR-4 expression through PKC-α and PKC-δ, respectively." (PMID 39947694, 2025).
Hyperglycemia (continued). "Hyperglycaemia in TLR2−/− mice occurred despite a marked increase in basal serum insulin levels at 9 months of age, indicating that TLR2−/− mice were becoming more resistant to insulin than their WT counterparts with age." (PMID 36555322, 2022). "Compared to sustained hyperglycemia, glycemic fluctuation led to further increase in IL-1β, TNFα, RANKL, TLR2/4, IRAK1, and TRAF6 mRNA expression in peri-implant gingival tissues." (PMID 34401982, 2021). "In contrast, islets pretreated with PGN (a TLR2 agonist) failed to reverse hyperglycemia, whereas PGN-treated TLR2-/- islets successfully normalized blood glucose levels." (PMID 40969771, 2025).
pancreatic cancer (27 papers, 2007 to 2025). "Studies have shown that among many TLR subtypes, TLR2 is highly overexpressed in pancreatic cancer, and its expression is associated with cancer aggressiveness." (PMID 38110966, 2023). "However, the association between TLR2 stimulation and tumor-genesis of pancreatic cancer and underlying mechanism need to be further elucidated." (PMID 38110966, 2023). "Consequently, TLR2, -4, and -9 are highly suspected to play a role in inflammation linked cancers such as pancreatic cancer." (PMID 27941651, 2016). "The administration of a humanized anti-TLR2 mAb, tomaralimab, in human tumor xenograft models of gastric and pancreatic cancers markedly inhibited the growth of tumors exhibiting high TLR2 expression and/or activation." (PMID 40640149, 2025). "Recent studies have demonstrated that Tlr2 can inhibit proliferation and inflammation in pancreatic cancer cells via the PI3K-AKT signaling pathway." (PMID 40787440, 2025). "Further, in our quest to identify the executor pathway for pancreatic cancer cell death, we found Caspase 8 to be significantly increased in cells expressing TLR2- and TRL9-specific intrabodies compared to the control cells." (PMID 38390872, 2024). "More recently, we described in advanced stage pancreatic cancers overexpressed TLR2, TLR4, TLR7, and TLR9 predominantly in tumor cells rather than tumor-infiltrating immune cells, making TLR inhibition strategies in this tumor even more interesting." (PMID 38390872, 2024). "Ex vivo fluorescence imaging and histologic analyses performed on the resected pancreatic tumors determined that all resected tumors were fluorescently labeled and TLR2-positive." (PMID 39320054, 2024). "In pancreatic cancer, the expression of TLR2 and TLR4 is mainly increased, and is associated with higher mortality,while TLR9 shows a downward trend in pancreatic cancer." (PMID 38110966, 2023). "In summary, Robinin inhibited cell migration, proliferation, and attenuated EMT perhaps via regulating inflammatory microenvironment in pancreatic cancer cells through targeted on TLR2- PI3k-AKT signaling pathway." (PMID 38110966, 2023). "Our study shows that Robinin, as an inhibitor of TLR2, significantly inhibits the proliferation and migration of pancreatic cancer cells, which is reversed by the combination of CU-T12-9 and Robinin." (PMID 38110966, 2023). "Serum Amyloid A1 (SAA1), another protein induced in pancreatic cancer cells, attracts neutrophils to the tumor nest by interacting with TLR2 (Toll-Like Receptor 2)." (PMID 37835519, 2023). "Robinin exerts anti-tumor effect perhaps via downregulating inflammation and EMT in pancreatic cancer cell through inhibiting TLR2-PI3k-AKT signaling pathway." (PMID 38110966, 2023). "In pancreatic cancer, increased TLR2 expression has a controversial role in the regulation of the pathophysiology of this neoplasia." (PMID 34884547, 2021). "Nevertheless, here we show that in the setting of pancreatic cancer, tumor-promoting effects of P. gingivalis are TLR2-independent, and enhanced by increasing the ability of bacteria to survive within the cells." (PMID 32824786, 2020). "We analyzed the expression of TLR2, -4, and -9 in primary human cancers and their impact on tumor growth via induced activation in several established pancreatic cancers." (PMID 27941651, 2016). "TLR mRNA was detected in all investigated cell lines indicating constitutive expression of TLR2, -4, and -9 in unstimulated human pancreatic cancer cells." (PMID 27941651, 2016). "We demonstrated that all three receptors TLR2, -4, and -9 are constitutively expressed in the analyzed established and primary pancreatic cancer cell lines." (PMID 27941651, 2016). "In the here presented study, we clearly demonstrated for the first time that ligation of TLR2, -4, and -9 results in increased tumor cell proliferation in pancreatic cancer." (PMID 27941651, 2016).
pancreatic cancer (continued). "This phase I/II trial examined safety and efficacy of the toll-like receptor 2/6 agonist MALP-2 in combination with gemcitabine in patients with incompletely resectable pancreas carcinomas." (PMID 17667928, 2007). "MALP-2 is a toll-like receptor 2/6 agonist, acts as an immunological adjuvant, and has been described recently to prolong survival in a mouse model of an orthotopic, syngeneic pancreas tumour." (PMID 17667928, 2007). "To detect signaling pathways that may be involved in pancreatic cancer cell death through TLR2 and TLR9 intrabody-mediated intracellular inhibition, we performed a Western blot analysis of STAT3 phosphorylation changes in the treated cells." (PMID 38390872, 2024). "Considering the high expression of TLR2 in pancreatic cancer and higher mortality, we speculated that Robinin (TLR2inhibitor) may play a positive role in pancreatic cancer therapy." (PMID 38110966, 2023). "Although PDAC cells are reported to express some Toll-like receptors, and P. gingivalis induces proliferation of oral epithelial tumor cells in a TLR2-dependent manner, we found that pancreatic tumor cell proliferation is enhanced by P. gingivalis independently of TLR2." (PMID 32824786, 2020). "TLR2 activation for instance, has been suggested as a possible therapeutic target, with local administration of a TLR2/6 agonist resulting in reduced tumor growth and prolonged survival in a pancreatic carcinoma mouse model." (PMID 32582207, 2020). "In summary, our results suggest that combining radiotherapy and an HMGB1 inhibitor, or targeting TLR2, may be considered a new therapeutic strategy to avoid pancreatic-carcinoma relapse and distant metastasis." (PMID 29615080, 2018). "Interestingly, more recent data point to tumor cell located TLR2 and -9 as effective markers to distinguish cancerous from normal epithelial cells in human pancreatic cancer." (PMID 27941651, 2016). "In this study, we analyzed the expression of TLR2, -4, and -9 in pancreatic cancer." (PMID 27941651, 2016). "The primary pancreatic cancers and cell lines expressed TLR2, -4, and -9." (PMID 27941651, 2016). "Here, we analyzed whether other Toll like receptors such as TLR2, -4, and -9 are additionally expressed in pancreatic cancer and may influence tumor cell signaling and proliferation to elucidate their potential for therapeutic strategies in this devastating tumor." (PMID 27941651, 2016). "Consistently, preclinical studies using genetic or antibody-mediated TLR2 blockade (e.g., OPN-301) inhibited tumorigenesis in gastric and pancreatic carcinomas, and head and neck cancers." (PMID 41375047, 2025). "In this study, we tested, for the first time, an intrabody-mediated TLR blockade in human TLR2- and TLR9-expressing pancreatic cancer cells for its effects on inflammatory signaling-mediated tumor growth." (PMID 38390872, 2024). "We found that TLR2 and TLR9, along with TLR4, play an important role in the growth of pancreatic cancer." (PMID 38390872, 2024). "In this study, we consequently targeted both TLRs (TLR2 and TLR9) using ER intrabodies in pancreatic cancer cells to prove their inhibitory effects on tumor growth." (PMID 38390872, 2024). "Recently, two intrabodies were selected, blocking TLR2 and TLR9 and inhibiting ex vivo inflammation-mediated pancreatic cancer cell growth." (PMID 39769267, 2024). "Therefore, we speculated that TLR2 interference can similarly regulate tumor microenvironment so as to minimize pan-cancer cell growth and attenuate metastasis, which would be a good candidate of pancreatic cancer medical therapy." (PMID 38110966, 2023). "In particular, in pancreatic cancer cells, upon the binding of HMGB1 (High mobility group box1) to TLR2, the PI3K/pAKT pathway is activated with subsequential induction of the epithelial-mesenchymal transition necessary for the metastatic phenotype." (PMID 34884547, 2021).
pancreatic cancer (continued). "Irradiated pancreatic cancer cells secrete HMGB1 and engage TLR2 to significantly promote cell migration." (PMID 33922955, 2021). "In the present study, HMGB1/TLR2, dependent on the PI3K/Akt signaling pathways, induces pancreatic cancer cells’ EMT and metastasis." (PMID 29615080, 2018). "PAUF is a ligand for toll-like receptor 2 (TLR2) and TLR4 and can promote the migration, invasion, proliferation, angiogenesis, and CXC receptor type 4 (CXCR4)–mediated metastasis of pancreatic cancer cells." (PMID 30115834, 2018). "In RT-qPCR, elevated relative gene expression of TLR2 (fold difference, FD = 29.8, p < 0.05), TLR4 (FD = 39.9, p < 0.005), and TLR9 (FD = 10.3, p < 0.005) was observed in pancreatic tumor tissues compared to normal tissues." (PMID 27941651, 2016). "The purpose of our study was to define the toxicity and efficacy of the toll-like receptor 2/6 agonist MALP-2 in combination with gemcitabine for the treatment of unresectable pancreas carcinoma." (PMID 17667928, 2007). "TLR2 and TLR9 expression was demonstrated to be upregulated in human PDACs, which was confirmed by our previous data and is listed in detail for human PDACs and established pancreatic cancer cell lines, including PANC-1 and BXPC-3." (PMID 38390872, 2024). "To investigate the potential of TLR2 and TLR9 inhibition in pancreatic cancer cells and its efficacy in tumor cell death, we developed pCMV Myc NCAM1, pCMV Myc TLR2, and pCMV Myc TLR9 plasmids expressing NCAM1 intrabodies (control intrabodies) and TLR2- and TLR9-specific intrabodies." (PMID 38390872, 2024). "We performed proof-of-concept studies to investigate whether TLR2 and TLR9 intrabodies that we generated could inhibit pancreatic cancer cell growth, decrease inflammatory markers, and induce apoptosis." (PMID 38390872, 2024). "Targeting TLR-mediated inflammatory signaling and, particularly, TLR2 and TLR9 may therefore be beneficial for patients with pancreatic cancer." (PMID 38390872, 2024). "To conclude, our results demonstrate the TLR2 and TLR9-specific intrabody-mediated signaling pathway inhibition of autoregulatory inflammation inside cancer cells and their proliferation, resulting in the suppression of pancreatic tumor cell growth." (PMID 38390872, 2024). "We have previously reported the high and broad expression of TLR2 among human pancreatic tumors and low expression of TLR2 in most non-vital tissues." (PMID 39320054, 2024). "Thus, our results confirm that TLR2- and TLR9-specific intrabodies inhibit pancreatic tumor cell growth." (PMID 38390872, 2024). "We observed that TLR2 protein expression was significantly inhibited and the PI3k/ATK pathway was activated after Robinin treatment, leading to proliferation and migration of pancreatic cancer cells." (PMID 38110966, 2023). "Subsequently, the stimulation of TLRs can actuate some adverse protumoral signaling pathways, such as TLR2, TLR4, and TLR9, which activate signaling pathways and anti-apoptotic Bcl-xL expression in terms of tumor cell activation and proliferation in pancreatic cancer." (PMID 33505964, 2020). "Furthermore, dying cell derived HMGB1 activates TLR2/YAP/HIF-1α pathways and induces neighboring CD133− pancreatic cancer cells dedifferentiation, which is an important signaling event underlying tumor relapse following radiotherapy." (PMID 31558702, 2019). "It has been reported that TLR2 is present in over 70% of pancreatic tumors and in cell lines from metastases, but not in normal pancreas tissue." (PMID 29615080, 2018). "Interestingly, stimulation of TLR9 and in part TLR2 resulted in upregulated VEGF gene expression (BxPC-3) and particularly of PDGF in all three analyzed human pancreatic cancer cell lines." (PMID 27941651, 2016).
pancreatic cancer (continued). "However, it has recently been shown that ligands within the gut microbiome of pancreatic cancer patients are recognized by TLR5, which, upon interaction with TLR2, activates a signaling cascade that leads to the cancer growth enhancement and to the suppression of innate and adaptive immune response." (PMID 34884547, 2021). "Moreover, HMGB1-induced pancreatic cancer cells’ invasion and metastasis was mediated by the receptor for TLR2, rather than TLR4 or RAGE." (PMID 29615080, 2018). "To dissect the effects of TLR activation, we treated two of the established pancreatic cancer cell lines (BxPC-3 and MIAPaCa-2) and one primary pancreatic cancer cell line (PaCaDD135) with TLR specific ligands (LTA for TLR2, LPS for TLR4, ODN for TLR9) and a non-specific ligand (HMGB1)." (PMID 27941651, 2016). "Western blot analysis of pancreatic tissue showed no protein expression of TLR2, -4, and -9 in normal pancreatic tissue (NT) compared to increased expression in tissue of chronic pancreatitis (CP) and in particular in primary pancreatic cancer at all stages (UICC I, IIA, IIB, III, and IV)." (PMID 27941651, 2016). "Expression of TLR2, -4, and -9 was analyzed by RT-qPCR and Western blot in five established human pancreatic cancer cell lines (Panc1, MIAPaCa-2, BxPC-3, AsPC-1, and SW1990) as well as in three primary human pancreatic cancer cell lines (PaCaDD135, PaCaDD159, and PaCaDD185)." (PMID 27941651, 2016). "Additionally, we extended current knowledge about the expression of TLR2, -4, and -9 in the various established to non-commercially available primary human pancreatic cancer cell lines." (PMID 27941651, 2016).